FAP (fibroblast activation protein alpha)
Diseases named in the same sentence as FAP in open-access papers (continued):
Sharing a sentence is not in itself a finding about the gene and the disease.
tumor (continued). "First, the preclinical tumor model involved transfected cell lines with extremely high FAP/SSTR2 expression." (PMID 38176714, 2024). "Specifically, CAFs express a transmembrane protein called fibroblast activation protein (FAP) that is involved in tissue remodeling and tumor growth." (PMID 39065684, 2024). "The antitumor effects were observed in fully immunoreactive mice but not in immunodeficient mice, suggesting that the depletion of FAP+ cells reduce tumor growth in an immune-dependent manner." (PMID 39239526, 2024). "Given the supporting role of CAFs in tumor growth and metastasis, we first confirmed the contribution of FAP+CAFs in NSCLC." (PMID 38459511, 2024). "As the primary anti-tumor effector cells, CD8 T and NK cells were enumerated in the tumor before and 24 h after anti-FAP NIR-PIT." (PMID 38275890, 2024). "In this study, tumor growth was evaluated after FAP-targeted NIR-PIT in a syngeneic allograft model." (PMID 38555315, 2024). "In recent years, FAP has attracted considerable attention due to its specific upregulation in multiple types of tumor cell populations, including cancer cells in various cancer types, making FAP a potential target for therapy." (PMID 36825204, 2023). "The elucidation of FAP’s role in enhancing NK cell migration and tumor infiltration presents a promising avenue for the development of novel immunotherapeutic strategies in cancer treatment, potentially improving the efficacy of NK-cell based therapies." (PMID 38196606, 2023). "In this study, we found that FGF20 was specifically detected in FAP(+) CAFs areas that were closely located to PanCK(+) tumor epithelial cells that had positive FGFR2 detection at EOCC tumor invasive margin." (PMID 37964075, 2023). "Then TNM plot online server was used to compare expression of FAP mRNA in normal, tumor and metastasis sites." (PMID 37325617, 2023). "Nevertheless, the successful FAP targeting by [68Ga]Ga-DATA5m.SA.FAPi provides a strong evidence of the otherwise successful strategy of tumor stroma targeting." (PMID 37284857, 2023). "Other preclinical studies are trying to image FAP expression on activated fibroblasts of the tumor stroma, with the aim of predicting and monitoring therapeutic response to FAP-targeted CAR T cell therapy." (PMID 37174086, 2023). "The LUMIERE trial is a phase I/II study to evaluate the safety, dosimetry, pharmacokinetics, and preliminary anti-tumor activity of 177Lu-FAP-2286 in patients with advanced or metastatic solid tumours." (PMID 39355052, 2023). "After COL1A1 knockout, Western blot was employed to examine the expression of fibrosis-related proteins (E-cadherin, α-SMA, FAP, and Cav-1) in the tumor microenvironment, aiming to determine any alterations in matrix fibrosis levels." (PMID 38045487, 2023). "To improve the tumor-to-background image contrast, we need to develop tracers that can be rapidly excreted from the body, but specifically bind to and be retained in FAP-expressing tumors." (PMID 36986548, 2023). "The findings from immunohistochemical analyses conducted on extracranial tumor tissues indicate that elevated FAP expression is indicative of an unfavorable prognosis, suggesting a significant involvement of FAP in tumorigenesis." (PMID 37864148, 2023). "The results of our study indicate a significant elevation in serum FAP levels as tumor progression occurs, suggesting that serum FAP has potential as a valuable tool for disease monitoring and as a marker for tumor progression." (PMID 37864148, 2023). "The diagnostic and therapeutic potential of the agents labeled with 68Ga and 177Lu was assessed in several tumor models exhibiting different levels of FAP expression." (PMID 38706713, 2023). "To determine if FAP inhibition also reduced donor NK cell migration and tumor lysis, we repeated these experiments with NK cells from two donors." (PMID 38196606, 2023).
tumor (continued). "For instance, [68Ga]Ga-FAPI-04, a quinoline-based FAP-targeting tracer, has been shown to have faster pharmacokinetics, higher tumor uptake, and superior tumor-to-background contrast in patients with various cancers when compared with [18F]FDG." (PMID 36770755, 2023). "Public data analysis revealed that FAP expression has significant immune correlations with multiple tumor tissues, and single-cell analysis data show the specific expression of FAP in CAFs from PAAD patient." (PMID 38031188, 2023). "HNSCC tumor-bearing mice were used to evaluate the feasibility of [68Ga]Ga-FAP-2286-ICG for tumor localization and guided surgical resection of HNSCC tumors." (PMID 38026901, 2023). "The most important challenges of FAP TRT are related to the retention time of FAP tracers in tumor, which is pivotal to enable tumoricidal doses." (PMID 36813980, 2023). "PWT in dogs and UPS in humans were the entities with the highest FAP expression score, largest FAP-stained area, and highest intensity of staining in tumor tissue." (PMID 37727209, 2023). "This study designed a novel fluorescent probe targeting FAP using the high tumor retention cyclic peptide FAP-2286 and the FDA-approved fluorescent dye ICG." (PMID 38026901, 2023). "Since on some tumour cell lines expression of FAP is observed, we investigated the binding of DTPA-700DX-MB to PDAC299 cells, but no binding or light-induced cytotoxicity was observed." (PMID 37408254, 2023). "Activation of CAFs, particularly in the early development phase, leads to FAP overexpression both in tumor cells and the surrounding stromal component in CRC and other GI malignancies." (PMID 37370912, 2023). "In the MCA205-mFAP model, tumor inhibition with combination 177Lu-FAP-2287 plus anti-PD-1 was observed on day 8 pi with heightened immune responses but by day 13 pi tumor control was lost perhaps in part reflecting immune pro-inflammatory signaling subsiding." (PMID 37086273, 2023). "Up-regulation of FAP in gastrointestinal cancers was primarily expressed in fibroblasts and contributes to tumor cells motility, macrophages infiltration and M2 polarization, revealing the multifactorial role of FAP in gastrointestinal cancers progression." (PMID 37325617, 2023). "FAP-targeted molecular imaging radiotracers have shown promising results; however, rapid clearance and inadequate tumor retention seem to be a recurring limitation." (PMID 36813980, 2023). "The vaccine achieved this by inducing strong and specific immune responses mediated by cytotoxic T lymphocytes (CTLs) against tumor cells and FAP + CAFs." (PMID 37641132, 2023). "As key cells involved in pro-tumour angiogenesis, HSCs have been demonstrated to upregulate fibroblast activation protein alpha (FAPα) and increase CXCL5 secretion, as regulated by cancer cell-secreted fibroblast growth factor-binding protein 1 (FGFBP1)." (PMID 37480104, 2023). "The findings based on two-photon imaging were confirmed by the multiplex IF staining of serial sections, further indicating that FAP-CAR T cells can overcome the stromal barrier to infiltrate tumor nests." (PMID 37607999, 2023). "Outgoing communication pattern analysis also suggested a coordinated pro-tumor signaling pathway between FAP + and MFAP5 + fibroblasts, which have long been verified as a tumor-driven stromal population." (PMID 37344903, 2023). "FAP-based Whole-Cell Tumor Vaccine (WCTV) was developed in another study in which inactivated tumor cells expressed FAP protein." (PMID 37316886, 2023). "Here we show that human NK cells express FAP, which is a key regulator of NK cell migration, invasion, extravasation and tumor infiltration." (PMID 38196606, 2023). "Another chemotherapy drug, cyclophosphamide, together with FAPα-targeted modified vaccinia Ankara, have been shown to be effective in overcoming immunosuppression and improving specific anti-tumor immune responses." (PMID 37496657, 2023).
tumor (continued). "To verify these findings in vitro, we used LIHC as example and over-expressed FAP in human hepatic stellate LX2 cells, a main cell type that produce FAP in tumor tissues, and then investigate its role on LIHC cells as well as macrophages." (PMID 37325617, 2023). "A novel strategy involves targeting the fibroblast activation protein (FAP), abundantly expressed within the tumor stroma." (PMID 37760801, 2023). "FAP+ cells can both promote tumor progression directly and present a barrier to immunotherapies through the production of ECM and direct signaling pathways." (PMID 36672284, 2023). "GSE39396 dataset contains cell data for the following cell populations EPCAM(+) tumor epithelial cells, FAP(+) CAFs, CD45(+) leucocytes, and CD31(+) endothelial cells." (PMID 37964075, 2023). "We observed a significant correlation between FAP elevation and tumor volume, as well as the depth of tumor infiltration, in BRCA, COADREAD, GBMLGG, STES, STAD, THYM, ACC, and SKCM." (PMID 37490719, 2023). "Apparently, there is an autoregulatory TGFβ loop in FAP-positive cell lines, which to some extent can mimic complex intratumoral interactions, when stroma–tumor paracrine signals serve to feed each other by repeatedly reflecting and multiplying." (PMID 37509656, 2023). "While the FAP-targeting agent ensures uptake in the tumor stroma, the cross-fire effect of the radiolabeled (alpha or beta emitting) radionuclides deliver tumoricidal doses to the ECM including the cancer cells." (PMID 36813980, 2023). "From previously published studies, FAP-specific CAR-T cells can kill most FAP+ cells, including CAFs, and prevent the growth of tumor stroma, which enhances the absorption of chemotherapy drugs and has anti-tumor benefits." (PMID 37784082, 2023). "Additional work in immunocompetent mouse tumor models developing more translationally relevant FAP expressing CAFs is warranted to further investigate the potential of beta-emitters in targeting the TME." (PMID 37086273, 2023). "Expression of receptors via FAP or integrins β3 immunostaining intensity and percentage of positive tumor cells were scored." (PMID 37284441, 2023). "Preclinically, we evaluated the immune modulation and anti-tumor efficacy of FAP-2287, a murine surrogate for FAP-2286, conjugated to the radionuclide lutetium-177 (177Lu) as a monotherapy and in combination with a PD-1 targeting antibody." (PMID 37086273, 2023). "As a proof of concept experiment, we set out to determine if NK cells engineered to overexpress FAP displayed enhanced infiltration into in a human tumor murine model." (PMID 38196606, 2023). "FAP has been a target of interest for anti-tumor vaccination in a strategy to target both tumor cells and immunosuppressive cancer-associated fibroblasts." (PMID 36765578, 2023). "Although the positive expression of FAP (especially FAP-α) cannot be confirmed in several tumor cell lines with Western blot or QT-PCR techniques, it can be readily detected in tumor stroma." (PMID 37057133, 2023). "The extensive expression of FAP makes it an attractive target for both imaging and therapy of a broad spectrum of tumours." (PMID 37608378, 2023). "FGF20 mRNA levels were significantly upregulated in FAP(+) CAFs at the tumor invasive margin of EOCC compared to LOCC tumors and showed a significant positive correlation (r > 0.6) with 15 of 17 DEGs of WNT signaling in EOCC." (PMID 37964075, 2023). "Immunohistochemical FAP expression was high on tumor stroma (∼90% of cells positive), whereas GLUT1 expression was high on tumor cells (∼80% of cells positive)." (PMID 37024301, 2023). "In 30 out of 50 pairs, FAP is reduced in the first metastasis compared to the primary tumor, while it remains stable in 13 out of 50 pairs and increases in 7 out of 50 pairs." (PMID 37892020, 2023). "Here, our goal is to develop PSMA/FAP bispecific radioligands with comparable or even higher tumor uptake compared to the PSMA- and FAP-targeting monospecific tracers." (PMID 36770755, 2023).
tumor (continued). "FAP expression at high levels was reported in malignant cells and multiple cell types of the tumor microenvironment, such as endotheliocytes, pericytes, and cancer-associated fibroblasts (CAFs)." (PMID 36825204, 2023). "As an analog of DOTA-FAPI-04 and proved in this research, 99mTc-HYNIC-FAPI-04 SPECT/CT was sensitive to tumor progression, such as tumorous volume and FAP expression, providing a monitoring method for dynamic changes in tumor progression." (PMID 36986521, 2023). "The use of vaccinia virus expressing FAP in combination with vaccinia virus expressing VEGF has improved tumor control efficacy in tumor xenograft model when compared to respective monotherapy." (PMID 37035187, 2023). "Although FAP-specific CAR-T cells can all produce limited anti-tumor effects, they also produce serious side effects, such as bone marrow toxicity." (PMID 37007004, 2023). "Fibroblast activation protein (FAP) offers a promising target for cancer therapy since its functions contribute to tumor progression." (PMID 37892020, 2023). "The dynamic serum FAP effectively addresses the limitations of MRI in differentiating between radiation necrosis and tumor progression." (PMID 37864148, 2023). "The serum levels of FAP exhibited a significant increase in the presence of recurrent tumor, whereas the serum levels of FAP displayed fluctuations in accordance with the condition of the tumor." (PMID 37864148, 2023). "TNFα can stimulate fibroblast activation in some circumstances, but it is also known to be suppressed by the tumor-promoting immunosuppressive activities of FAP+ fibroblasts." (PMID 36793444, 2023). "Multiple clinical trials are currently underway to evaluate FAP-targeted imaging tracers, which are evolving to increase tumor retention time and uptake, and are even more tumor-specific." (PMID 36900136, 2023). "Spontaneous tumors from KPC mice were also stained and showed an abundance of FAP+ stromal cells surrounding PanCK+ tumor cells." (PMID 37607999, 2023). "This strategy was meant to kill cancer cells and simultaneously decrease the immunosuppressive function of FAP+ stromal cells in the tumor microenvironment (TME)." (PMID 36717905, 2023). "Based on our findings, it can be inferred that the integration of serum autoantibody relative FAP level and MRI examination has the potential to enhance the precision of tumor progression monitoring in a clinical setting." (PMID 37864148, 2023). "In this model, we again saw only modest effects from the Meso-CAR T cells but observed more robust inhibition of tumor growth with the FAP-CAR T cells compared with MigR control and Meso-CAR T cells, monitored by non-invasive ultrasound imaging." (PMID 37607999, 2023). "A similar observation was also reported when oncolytic adenovirus ICOVIR15K was used to generate ICO15K-FBiTE (anti-human CD3 single-chain variable fragment (scFv) linked to an anti-murine and human FAP scFv and assessed in HT1080 and A549 tumor cell lines." (PMID 37035187, 2023). "FAP plays a key role in promoting tumor progression and metastasis, further shaping the immunosuppressive tumor microenvironment." (PMID 37099374, 2023). "In conclusion, applications of the FAP aptamers screened in the current study are promising for the diagnosis and treatment of tumor diseases in future research work." (PMID 36838669, 2023). "FAP labeling in tumor, peritumoral, healthy skin, and inflamed tissue samples was quantified using a visually assessed semiquantitative expression score and digital image analysis." (PMID 37727209, 2023). "Reportedly, the expression of FAP is enhanced at tumor boundaries and invasive frontiers, such as tumor cell protrusions, under the microscope." (PMID 37918866, 2023). "Subsequently, we examined the expression levels of FAP in 36 tumor tissues and ranked them from low to high." (PMID 37490719, 2023).
tumor (continued). "The role of FAP expression in tumor immunotherapy was investigated using the IMvigor210 cohort (BLCA) and the GSE78220 cohort (SKCM)." (PMID 37490719, 2023). "This vaccine induced a strong CTL immune response against tumor cells and FAP+CAF and remodeled the immunosuppressive TME in lung, colon, breast, and melanoma cancer models." (PMID 37915578, 2023). "A preclinical study demonstrated rapid accumulation and long retention of lutetium-177 (177Lu)-radiolabeled FAP-2286 in FAP-positive tumors resulting in significant tumor growth suppression, with minimal uptake in normal organs." (PMID 37086273, 2023). "To compare the anti-tumor activity of FAP- and Meso-CAR T cells in vivo, we established subcutaneous 4662 PDAC tumors in syngeneic C57BL/6 mice." (PMID 37607999, 2023). "For example, FAP is activated by αvβ6-integrin during tumor progression, which contributes to the recruitment of relevant aggressive cytokines, including MMPs, in activated cancer-associated fibroblasts." (PMID 37006278, 2023). "Applying RF learning to transcriptomic data of 29 cancer entities, we identified the top 200 gene signatures, which were most discriminative regarding CXCR4/FAP high- vs. low-expressing tumor samples." (PMID 36672341, 2023). "Another study developed a tumor vaccine prepared from tumor-cell-derived exosome-like nanovesicles (eNVs-FAP), which demonstrated excellent anti-tumor effects in a variety of tumor-bearing mouse models." (PMID 37496657, 2023). "As an enzyme, FAP has di- and endoprolylpeptidase, endoprotease, and gelatinase/collagenase activities in the Tumor Microenvironment (TME)." (PMID 37316886, 2023). "At 1.5 h P.I., 99mTc-HYNIC-FAPI-04 uptake was clearly observed in FAP-positive U87MG tumor at 2.67 ± 0.35 %ID/mL." (PMID 36986521, 2023). "FGFR2 is upregulated in tumor epithelial cells, while FGF20 is increased in neighbor FAP(+) CAFs at EOCC tumor invasive margin." (PMID 37964075, 2023). "NGDSP analysis and cell deconvolution analysis demonstrated that FAP(+) CAF at EOCC tumor invasive margin showed WNT signaling upregulation." (PMID 37964075, 2023). "In NSCLC, FAP+aSMA+CAFs produce collagen, form multiple layers in tumours, and prevent T-cell contact with tumour cells." (PMID 37199594, 2023). "68Ga-FAPI-46 is a novel radioligand that binds to FAP in the tumor stroma and has shown high detection rates for stroma-rich tumors." (PMID 37024301, 2023). "FAP expression in tumor stroma is present in many cancers and has been suggested to be involved (among other things) in remodeling of the tumor environment." (PMID 38004406, 2023). "The combinatory therapeutic effect of an anti-PD-1 antibody and 177Lu-FAP-2287 was evaluated in vivo in the MCA205-mFAP tumor model." (PMID 37086273, 2023). "In the present study, the parameters of FAP uptake better evaluated the tumor withdrawal pattern, especially when 68Ga-FAPI PET/CT was done 1 wk before surgery." (PMID 37918866, 2023). "FAP was originally identified as an inducible antigen expressed on reactive stroma and represents one of the main markers of corrupted by tumor fibroblasts—CAFs." (PMID 37509656, 2023). "The SynCon FAP DNA vaccine synergized with other tumor-antigen-specific DNA vaccines showed a stronger anti-tumor activity than monotherapy, and the SynCon FAP DNA vaccine itself exerted remarkable antitumor effect in the TC-1, Brpkp110, and TSA tumor models." (PMID 37784082, 2023). "Fibroblast activation protein (FAP, FAP-α), a type-II transmembrane serine protease, acts on several hormones and extracellular matrix components and has an essential role in tumor biology." (PMID 36832085, 2023). "Consistent with our data above, we found pre-treatment of FAP-CAR T cells significantly enhanced the efficacy of the second treatment with Meso-CAR T cells in inhibiting tumor growth." (PMID 37607999, 2023).